SOCS5 (suppressor of cytokine signaling 5)
Diseases named in the same sentence as SOCS5 in open-access papers (continued):
Sharing a sentence is not in itself a finding about the gene and the disease.
tumor (36 papers, 2010 to 2025). "In conclusion, we demonstrated that SOCS5 is overexpressed in HCC patients and that high SOCS5 expression is associated with aggressive tumor features and poorer patient prognosis." (PMID 31406106, 2019). "Research has shown that the overexpression of SOCS5 promotes tumor growth and invasion through autophagy, which is mediated by the PI3K/AKT/mTOR signaling pathway." (PMID 41326907, 2025). "In our patient cohort, SOCS5 and RBMX in 6 pairs of matched HCC and adjacent non-tumor frozen tissues were detected by Western blotting, and we observed that both SOCS5 and RBMX were significantly higher expressed in HCC tissues." (PMID 38429411, 2024). "Among them, SOCS5 is expressed in a variety of adult tissues, playing anti-inflammatory, anti-tumor, anti-oxidative stress and other functions." (PMID 37828534, 2023). "Crucially, we explored the role of SOCS5 in hypoxia-induced HCC tumor metastasis in metastatic human HCC orthotopic nude mouse models using left hepatic artery and vein ligation (LHAVL) to simulate PM during surgery." (PMID 36319626, 2022). "We investigated the hypoxic tumor microenvironment, finding that SOCS5 promoted the invasion and migration of HCC cells by activating the PI3K/Akt/mTOR-HIF-1α signaling axis." (PMID 36319626, 2022). "Cancer cell-derived EV-associated with miR-9 activated the JAK/STAT pathway, which reduced levels of suppressor of cytokine signaling-5 (SOCS5), promoting endothelial cell migration and tumor angiogenesis." (PMID 35159299, 2022). "We further examined the in vivo anti-tumor effects of SOCS5 inhibition in lateral tail vein metastasis and subcutaneous tumorigenesis models." (PMID 36319626, 2022). "More importantly, we found that PM can promote HCC tumor metastasis in metastatic human HCC orthotopic nude mouse model, and HCC tumors with knockdown of SOCS5 were more resistant to hypoxia caused by PM." (PMID 36319626, 2022). "Among these sets, 21 (21/62, 33.9%) and 14 (14/62, 22.6%) tumor tissue samples displayed up-regulation and down-regulation of SOCS5 respectively compared to their corresponding normal tissue samples." (PMID 33758600, 2021). "For SOCS5, one study reporting increased expression and five studies reporting decreased expression in tumor tissues were identified." (PMID 34120621, 2021). "Considering this, miR-142-3p mimic led to a significant inhibition of STAT3 and SOCS5 in tumor tissues." (PMID 33987190, 2021). "The question remains as to why an opposite relationship exists in tumor tissue regarding the correlation between SOCS5 expression and PFS?" (PMID 33758600, 2021). "A lot of evidences suggest that SOCS5 serves as a tumor suppressor in cancers by negatively regulating JAK2/STAT3." (PMID 33935775, 2021). "H&E staining and immunohistochemical showed that leonurine together with miR-18a-5p suppression significantly destroyed the morphology of tumor tissues and increased the expression of SOCS5 protein." (PMID 33935775, 2021). "Why SOCS5 seemingly performs diametrically opposing functions in tumor pathogenesis across different cancer types, however, remains an outstanding question." (PMID 34059683, 2021). "The results indicated a significant reduction of STAT3, SP1, and SOCS5 mRNA expression in the splenocytes of CT-26 tumor-bearing mice treated with TEXomiR compared to both the TEX and PBS groups (P < 0.01)." (PMID 33987190, 2021). "In spite of these reports, however, the pro-oncogenic roles we describe for SOCS5 in TNBC cells are in agreement with prior (albeit fewer) reports indicating tumor-promoting activities for SOCS5." (PMID 34059683, 2021). "For instance, T-EVs transporting miR-9 stimulate EC migration and tumour angiogenesis via the reduction of suppressor of cytokine signalling 5 (SOCS5) levels and activation of the JAK/STAT pathway." (PMID 33081785, 2020).
tumor (continued). "For example, exosomal miR-9 secreted by tumor cells, activates the Janus kinase/signal transducers and activators of transcription JAK/SAT pathway by reducing cytocine signaling 5 (SOCS5) levels to promote tumor angiogenesis." (PMID 32257377, 2020). "The combined targeting of SOCS5 and the PI3K/Akt/mTOR pathway provides an attractive new option for impairing tumor metastasis, which is one of the main causes underlying the dismal prognosis of HCC patients." (PMID 31406106, 2019). "We retrieved the mRNA expression of SOCS5 from three published HCC datasets in the Oncomine database and observed significant overexpression of SOCS5 in HCC tissues compared to the non-tumor liver tissues in all the three datasets." (PMID 31406106, 2019). "SOCS5 is the Socs36E human ortholog and, as observed in flies, SOCS5 acts as a tumor suppressor in EGFR/RAS–dependent cell transformation assays." (PMID 31331981, 2019). "We validated this observation in our patient cohort using qPCR and western blotting of the matched HCC and adjacent non-tumor frozen tissues and similarly observed significant overexpression of SOCS5 in HCC." (PMID 31406106, 2019). "Using large independent datasets and our own patient cohort, we confirmed the significantly enhanced expression of SOCS5 in HCC tissues compared to non-tumor liver tissues." (PMID 31406106, 2019). "The miR-9 is secreted by tumor cells, and activates STAT3 in ECs by inhibiting SOCS5 levels, leading to migration of ECs and tumor angiogenesis." (PMID 28978186, 2017). "SOCS5 levels of expression were significantly lower in tumour tissue from patients with TNM-4 stage disease compared to normal background tissue; TNM-4 vs. background tissue [mean copy number 0.263 vs. 4318, 95% CI (-7867.49, -769), p = 0.019]." (PMID 20433750, 2010). "HCC patients with low expression of SOCS5 may be more tolerant to PM-induced changes in the hypoxic tumor microenvironment." (PMID 36319626, 2022). "The number of lung metastatic nodules and subcutaneous tumor volume and weight in nude mice inoculated with HCCLM3 LV-shSOCS5 cells were significantly reduced compared with the control group, indicating that the tumor behavior of HCCLM3 cells was significantly reduced upon inhibiting SOCS5 by shRNA." (PMID 36319626, 2022). "Some scholars also proposed the tumor inhibition effect of SOCS5 in HCC." (PMID 36319626, 2022). "This suggests that HCC patients with low SOCS5 expression were more tolerant to changes in the tumor-hypoxic microenvironment induced by PM, and that SOCS5 might play a crucial role in the tumor-hypoxic microenvironment." (PMID 36319626, 2022). "One possibility is that persistent expression of cytokines and growth factors in the tumor microenvironment might stimulate aberrant over-expression of SOCS5, and thus, the correlation of SOCS5 and unfavorable prognosis was observed." (PMID 33758600, 2021). "Multiple species of endogenous SOCS5 could be detected with the molecular weight around 55 to 60 KDa (KiloDalton) both in normal and tumor tissues." (PMID 33758600, 2021). "It is reasonable to speculate that SOCS5 expression in normal tissue plays an anti-tumor role which is mediated by regulating the oncogenic effects exerted by certain cytokines and growth factors to prevent disease progression." (PMID 33758600, 2021). "Interestingly, there was significantly different trend of SOCS5 expression between normal and tumor tissues in most of the tissue sets (35/62, 56.5%)." (PMID 33758600, 2021). "Growing evidence now points towards a role for SOCS5 as a tumor suppressor." (PMID 23990909, 2013). "Thus, we found that MSC-derived triggers induced LINC01119 expression in neighboring TNBC cells, which in turn stimulated SOCS5, leading to accelerated in vitro cancer cell growth, both in adhesion and in suspension, as well as accentuated in vivo tumor formation in xenografted mice." (PMID 34059683, 2021).
tumor (continued). "Furthermore, weak expression of SOCS5 in normal, but not in tumor tissue, was strongly associated with distant metastasis after surgery (P=0.004)." (PMID 33758600, 2021). "SOCS5, another common DEG identified in PRL signalling, is a member of the suppressor of cytokine signalling (SOCS) protein family with controversial tumour-promoting and tumour-suppressive roles in cancer." (PMID 35773139, 2022). "In an overexpressed SOCS5 orthotopic HCC model, we showed that LHAVL-induced HIF-1α expression promotes HCC tumor metastasis and, more importantly, that HCC tumors overexpressing SOCS5 undergo LHAVL, with a significant rise in metastatic ability." (PMID 36319626, 2022). "We also found a positive relationship between SOCS5 and HIF-1α, the core molecule of the hypoxic tumor microenvironment, at the RNA and protein levels via the cBioPortal website and the Human Protein Atlas website." (PMID 36319626, 2022). "To investigate the expression correlation between SOCS5 and EGFR, we detected the expression of SOCS5 and EGFR in 62 sets of adjacent normal and tumor tissues by western blot." (PMID 33758600, 2021). "Strong expression of SOCS5 in normal tissue was correlated with better PFS though without reaching statistically significance, but the opposite trend was observed in tumor tissue (P=0.070 and 0.011 respectively)." (PMID 33758600, 2021). "Similar to EGFRAP, SOCS proteins, such as Drosophila Socs36E and its human ortholog SOCS5, also contain an SH2 domain, are induced by EGF stimulation and behave as tumor suppressors in cooperation with the EGFR/Ras pathway." (PMID 34411095, 2021). "Of pertinence, STAT6 has been described to act as a tumor suppressor in breast cancer, providing a possible mechanism-of-action of LINC01119/SOCS5 in driving TNBC cell growth by curtailing STAT6 activation." (PMID 34059683, 2021). "This is opposed to a recent report suggesting a tumor-suppressive role of SOCS5 in HCC, whereby SOCS5 inhibition was observed to enhance anchorage-dependent and anchorage-independent colony growth of SNU398 and HepG2 cells." (PMID 31406106, 2019). "Clinically, the overexpression of SOCS5 in HCC patients was significantly correlated with aggressive tumor features such as increased AFP level, large tumor size, vascular invasion, and advanced TNM stage." (PMID 31406106, 2019). "We observed that SOCS5 was significantly overexpressed in HCC tissues, compared to adjacent non-tumor liver tissues, in both the public datasets and in our patient cohort." (PMID 31406106, 2019). "One study showed that microvesicles-derived miR-9 effectively reduced SOCS5 expression and activated JAK-STAT pathway, which promoted endothelial cell migration and tumour angiogenesis." (PMID 30001734, 2018). "Depletion of SOCS5/6 or upregulation of YAP1 can bypass the requirement for oncogenic Ras in anchorage independent growth in vitro and tumor formation in vivo." (PMID 25180228, 2014). "Notably, DDP treatment significantly increased SOCS5 and SOCS6 expression in tumor tissues, and this phenomenon was further enhanced after the knockdown of miR-424-5p." (PMID 38439876, 2024). "Interestingly, the role of SOCS5, SOCS6, JAK2/STAT3, and PI3K/AKT pathways in DDP resistance of tumor cells has been well documented." (PMID 38439876, 2024). "Considering these data and existing knowledge on HIF1A, we hypothesized that SOCS5 promotes the expression of HIF1A and affects the hypoxic tumor microenvironment." (PMID 36319626, 2022). "The development of a SOCS5-specific inhibitor, an indirect inhibitor of HIF-1α, might be effective at controlling PM-induced tumor micrometastases during HCC resection." (PMID 36319626, 2022). "SOCS5 functioned as a partner of LINC01119, and we found that it was both sufficient and necessary to promote TNBC cell growth across several TNBC cells and that it promoted tumor growth in nude mice." (PMID 34059683, 2021).
tumor (continued). "However, 14 and 22 of these studies showed statistically significant differences in SOCS5 and SOCS6 expression, respectively, between tumor and normal tissues." (PMID 34120621, 2021). "Hence, we posit that LINC01119 induces SOCS5 expression, which then inhibits STAT6, relieving its tumor-suppressive functions in TNBC cells." (PMID 34059683, 2021). "SOCS5/6 depletion also proved to be sufficient to support xenograft tumor formation by BJT/p53KD/p16KD/ST cells in vivo, without RasV12." (PMID 25180228, 2014). "Notably, the difference in expression between SOCS5 and EGFR of tumor tissue was negatively correlated with that of corresponding normal tissue in about half of the tissue sets (30/62, 48.4%) which revealed the possible negative regulating role of SOCS5 in EGFR expression." (PMID 33758600, 2021). "SOCS5 expression was significantly downregulated in 12‐month‐old non‐PH HBx transgenic livers compared with non‐transgenic livers but not in the transgenic livers at the time point of tumor formation after PH." (PMID 29729074, 2018). "More recently, epigenetic silencing of SOCS5 expression has been shown to correlate inversely with EGF-R expression in aggressive hepatocarcinoma, while down-regulation of SOCS5 expression by tumor-derived miR-9 results in enhanced JAK1/2 and STAT1/3 phosphorylation in endothelial cells." (PMID 23990909, 2013). "Although many tumor suppressor genes are silenced by DNA methylation during carcinogenesis, downregulation of SOCS3 and SOCS5 was not dependent on DNA hypermethylation." (PMID 25849377, 2015).
cancer (22 papers, 2010 to 2024). A tumor composed of atypical neoplastic, often pleomorphic cells that invade other tissues. "First, we found that MSCs, which stimulated LINC01119 in admixed cancer cells, also caused ~5 and ~2-fold enrichment of SOCS5 expression in co-cultured MDA-MB-231 and HCC1143 cells, respectively." (PMID 34059683, 2021). "miR-9 modulates the expression of e-cadherin and suppressor of cytokine signaling 5 (SOCS5) which cancer linked proteins." (PMID 27609145, 2016). "Suppressor cytokine signaling-5 (SOCS5) to date is recognized as a tumor suppressor in various types of cancer." (PMID 34666613, 2021). "SOCS5 is a member of the suppressor of cytokine signaling (SOCS) protein family with important yet incompletely understood biological functions in cancer." (PMID 31406106, 2019). "The prognostic role of SOCS5 is hardly understood in cancers." (PMID 33758600, 2021). "Importantly, LINC01119/SOCS5 repression severely impaired cancer cell growth, and the pathway served as a powerful prognostic indicator of adverse outcomes in TNBC patients." (PMID 34059683, 2021). "Moreover, the role of SOCS5 has been widely investigated in human cancers (exclude NSCLC), indicating that SOCS5 can be stably expressed in human cells and is involved in tumorigenesis." (PMID 32844573, 2020). "SOCS5 has also been shown to be downregulated in cancer cells, and may play a role in reducing tumor growth and angiogenesis." (PMID 27317770, 2016). "Here we provide a molecular explanation as to how these two distinct SOCS5 activities might be mediated, and hence how SOCS5 might impact on these cancer-promoting kinase cascades." (PMID 23990909, 2013). "The results indicated that the promoter methylation levels of SOCS1 (p– = 7.379E‐07), SOCS3 (p = 4.534E‐10), SOCS5 (p = 1E‐12), SOCS6 (p = 5.534E‐11), and CISH (2.273E‐05) were lower in cancer tissues than in normal tissues." (PMID 39307915, 2024). "We report that MSCs stimulate robust expression of LINC01119 in TNBC cells, which in turn induces suppressor of cytokine signaling 5 (SOCS5), leading to accelerated cancer cell growth and tumorigenesis." (PMID 34059683, 2021). "For SOCS5 and SOCS6, 413 and 412 studies of multiple cancer types were taken into consideration, respectively." (PMID 34120621, 2021). "SOCS5 is a potential negative regulator of EGFR, as has been demonstrated in both human cancer cells 25-26 and a Drosophila epithelial transformation model." (PMID 33758600, 2021). "Numerous researches have indicated that SOCS5 and SOCS6 act as cancer suppressors in NSCL." (PMID 38439876, 2024). "While SOCS5 may not be the only factor mediating DC dysfunction in cancer, it clearly contributes to DC defects in CLL patients." (PMID 27317770, 2016). "Thus the discrepancy of our conclusions may result from the differences in our assays; it is also possible that SOCS5 regulates HCC growth and progression in a complex manner, perhaps through the modulation of autophagy, which has been shown to be a double-edged sword in cancers, including HCC13." (PMID 31406106, 2019).